XRCC1 (X-ray repair cross complementing 1)
Diseases named in the same sentence as XRCC1 in open-access papers (continued):
Sharing a sentence is not in itself a finding about the gene and the disease.
head and neck cancer (14 papers, 2008 to 2023). A primary or metastatic malignant neoplasm affecting the head and neck. "Many studies have focused on XRCC1 SNPs and have shown an associated between these SNPs and the risk of several types of cancers, including head and neck cancer." (PMID 32212791, 2020). "In this study, we investigated the association between the most common polymorphism on XRCC1 gene, Arg399Gln, and the risk of head and neck cancer." (PMID 32212791, 2020). "Many studies have focused on XRCC1 Arg399Gln SNP and have shown its association with the risk of several types of cancers, including head and neck cancer." (PMID 32212791, 2020). "Recent studies have reported on the associated risk of XRCC1 polymorphism cross lifestyle factors in the progression of head and neck cancer." (PMID 24086310, 2013). "The genotype and allele frequency and odds ratios (OR) of the Arg399Gln polymorphism of XRCC1 gene in patients with head and neck cancer with different tumor size and lymph node status." (PMID 19284666, 2009). "The genotype and allele frequency and odds ratios (OR) of the Arg194Trp polymorphism of XRCC1 gene in patients with head and neck cancer with different tumor size and lymph node status." (PMID 19284666, 2009). "XRCC1 rs25487 is associated with reduced risk of minor radiotherapy-related/radiation-induced treatment response in esophageal cancer and increased risk of mucositis in head and neck cancer." (PMID 34094945, 2021). "Interestingly, a meta-analysis that focused on the association between Arg399Gln and head and neck cancer recommended further studies to assess Arg399Gln SNPs in XRCC1 as risk factors for developing head and neck cancer." (PMID 32212791, 2020). "In our study, we assessed two common polymorphisms of the XRCC1 gene that might influence DNA repair capacity and their association with head and neck cancer risk." (PMID 19284666, 2009). "Sequence variation in XRCC1 gene may alter head and neck cancer (HNC) susceptibility." (PMID 24086310, 2013). "To test this hypothesis, we performed a hospital based case-control study using a polymerase chain reaction-restriction fragment length polymorphism (PCR-RFLP) assay to genotype two polymorphisms of DNA repair gene XRCC1 Arg194Trp and Arg399Gln in relation to head and neck cancer susceptibility." (PMID 19284666, 2009). "Distribution of XRCC1 genotypes among head and neck cancer cases and controls included in the meta-analysis." (PMID 24086310, 2013). "Although the functional significance of XRCC1 polymorphism has not yet been fully elucidated, due to smoking and alcohol consumption attitude it may increase risk of head and neck cancer occurrence." (PMID 19284666, 2009). "BZA treatment also markedly reduced chemo and radioresistance in head and neck cancer cells by downregulating ERCC-1, XRCC-1 and survivin expression." (PMID 28978005, 2017). "Combining ß-lapachone with XRCC1 knockdown or methoxyamine (MeOX), an apyrimidinic/apurinic (AP)-modifying agent, led to NQO1-dependent synergistic killing in PDA, NSCLC, breast and head and neck cancers." (PMID 26602448, 2015). "Haplotype analysis for XRCC1 (rs3213245, rs1799782, rs25489 and rs25487), RAD51 (rs1801320, rs1801321) and NBN (rs1805787, rs1805794) and radiation-induced oral mucositis and skin reactions in head and neck cancer patients." (PMID 24594932, 2014). "A study to determine whether DNA polymorphism of ERCC1 has predictive value in head and neck cancer patients showed that polymorphic variation in DNA repair genes (XPD and XRCC1, not ERCC1) is a powerful prognostic factor for the response to cisplatin in SCCHN patients." (PMID 18594541, 2008).
head and neck squamous cell carcinoma (14 papers, 2009 to 2024). A squamous cell carcinoma that arises from any of the following anatomic sites: lip and oral cavity, nasal cavity, paranasal sinuses, pharynx, larynx, and salivary glands. "Various studies have examined the association between XRCC1 Arg194Trp polymorphism and head and neck squamous cell carcinoma (HNSCC) susceptibility with contradictory results." (PMID 36573562, 2023). "More extensive studies with larger sample sizes are needed to validate the genetic effects of XRCC1 polymorphisms on head and neck squamous cell carcinoma." (PMID 32212791, 2020). "In a study of 101 patients with head and neck squamous cell carcinoma, the development of grade ≥2 mucositis was increased in patients with XRCC1 rs25487 A allele (HR=1.72)." (PMID 29108254, 2017). "Epidemiologic studies have reported the association of X-ray repair cross-complementary group 1 (XRCC1) Arg399Gln polymorphisms with susceptibility to squamous cell carcinoma of the head and neck (HNSCC)." (PMID 24205020, 2013). "Haplotypes distribution and frequencies of XRCC1 gene polymorphisms in squamous cell carcinoma of the head and neck (HNSCC) patients and the controls." (PMID 19284666, 2009). "The genotype and allele frequency and odds ratios (OR) of the Arg399Gln polymorphism of XRCC1 gene in squamous cell carcinoma of the head and neck (HNSCC) patients and the controls with positive smoking status." (PMID 19284666, 2009). "Single nucleotide polymorphism of XPD and XRCC1 (at C26304T and G28152A) genes are reported as relatively high in younger head and neck squamous cell carcinoma (HNSCC) patients." (PMID 38046721, 2023). "Higher XRCC1 expression is associated with poor response and survival, particularly in patients with head and neck squamous cell carcinoma (HNSCC) receiving chemoradiation." (PMID 35996502, 2022). "We performed a case-control study to test the association between two common single nucleotide polymorphisms (SNPs) of XRCC1 gene with human head and neck squamous cell carcinoma (HNSCC)." (PMID 19284666, 2009). "In head and neck squamous cell carcinoma (HNSCC) patients, XRCC1 is associated with poorer survival, especially in patients receiving combined chemoradiotherapy." (PMID 34766149, 2021). "Furthermore, we examined the correlation between XRCC1 expression and clinical stages in head and neck squamous cell carcinoma (HNSC) and oral squamous cell carcinoma (OSCC)." (PMID 38217545, 2024). "XRCC1 and CEP55 are supposed to be direct transcriptional targets of FOXM1 in serous EOC and head-and-neck squamous cell carcinoma, respectively." (PMID 28482906, 2017).
prostate carcinoma (13 papers, 2011 to 2025). A carcinoma that arises from epithelial cells of the prostate gland. "Similar to APEX1 SNPs, several SNPs in other DNA repair genes, specifically OGG1, LIG3, and XRCC1, were associated with prostate cancer among men taking finasteride." (PMID 35096612, 2021). "LIG3-rs1052536 and XRCC1-rs25489 were suggestively associated with reduced risk of high-grade prostate cancer (per minor allele: both p-trend=0.04)." (PMID 35096612, 2021). "A previous study showed that XRCC1 Arg399Gln variant genotypes was associated with a heavy increased risk of prostate cancer in heavy smokers, and their results are in line with ours." (PMID 26101477, 2015). "A significant association between the XRCC1-Arg399Gln polymorphism and prostate cancer was observed in African and Asian populations under only the homozygote model and the recessive model." (PMID 25927275, 2015). "In view of some limitations of our meta-analysis, well-designed case control studies and larger population sizes are needed to validate the role of XRCC1 Arg399Gln and Arg280His polymorphisms in the development of prostate cancer." (PMID 25927275, 2015). "A significant association between the XRCC1-Arg280His polymorphism and prostate cancer susceptibility was found under the heterozygote model and the dominant model." (PMID 25927275, 2015). "A significant association between XRCC1-Arg280His and prostate cancer risk was found under a heterozygote model, a recessive model, and a dominant model." (PMID 25927275, 2015). "Of the 14 case control studies, 5 were about the XRCC1-Arg280His polymorphism and susceptibility to prostate cancer; 4 were conducted in Asian populations; 7 were in Caucasian populations; and 5 were in African populations." (PMID 25927275, 2015). "We conducted a case-control study to examine the role of XRCC1 codons 194 (Arg>Trp), 280 (Arg>His) and 399 (Arg>Gln) polymorphisms in the risk of prostate cancer." (PMID 26101477, 2015). "Because there has been a debate regarding the relationship between the XRCC1-Arg399Gln and Arg280His polymorphisms and prostate cancer risk, we therefore performed this meta-analysis." (PMID 25927275, 2015). "And XRCC1-Arg280His polymorphism is likely to be related with prostate cancer risk under the heterozygote model and the dominant model." (PMID 25927275, 2015). "Genotype frequencies of XRCC1 codons 194 (Arg>Trp), 280 (Arg>His) and 399 (Arg>Gln) polymorphisms in prostate cancer cases and controls." (PMID 26101477, 2015). "Study characteristics from published studies on the relationship between condon 399 polymorphisms in XRCC1 gene and prostate cancer." (PMID 26649000, 2015). "Our results show an increased risk for prostate cancer in individuals with XRCC1 194 (Arg>Trp) polymorphism, and a significant interaction between XRCC1 194 (Arg>Trp) polymorphism and tobacco smoking, alcohol drinking and family history of cancer." (PMID 26101477, 2015). "A significant association between the XRCC1-Arg399Gln polymorphism and prostate cancer risk was found under a homozygote model and a recessive model." (PMID 25927275, 2015). "Additionally, there were suggestions that LIG3-rs1052536 and XRCC1-rs25489 were associated with reduced risk of high-grade prostate cancer (both per minor allele: p-trend=0.04)." (PMID 35096612, 2021). "In addition, XRCC1-rs25489 was associated with a significant decreased risk for high-grade prostate cancer." (PMID 35096612, 2021). "In summary, our meta-analysis evaluated all of the available published data, and the results suggested that a significant association between XRCC1-Arg399Gln and risk of prostate cancer was found under the homozygote model and the recessive model, particularly in Asian and Africa populations." (PMID 25927275, 2015). "Total and stratified analysis of condon 399 polymorphisms in XRCC1 gene on prostate cancer." (PMID 26649000, 2015).
prostate carcinoma (continued). "In conclusion, our results show an increased risk for prostate cancer in individuals with XRCC1 194 (Arg>Trp) polymorphism, and a significant interaction between XRCC1 194 (Arg>Trp) polymorphism and tobacco smoking, alcohol drinking and family history of cancer." (PMID 26101477, 2015). "Therefore, in this study, we conducted a case-control study to examine the role of XRCC1 codons 194 (Arg>Trp), 280 (Arg>His) and 399 (Arg>Gln) polymorphisms in the risk of prostate cancer." (PMID 26101477, 2015). "Second, we only investigated association between XRCC1 and risk of prostate cancer, and other DNA repaired genes may have interaction with XRCC1." (PMID 26101477, 2015). "Stratification analyses between XRCC1 194 (Arg>Trp)polymorphism and risk of prostate cancer." (PMID 26101477, 2015). "In this case-control study, we investigated that the role of XRCC1 codons 194 (Arg>Trp), 280 (Arg>His) and 399 (Arg>Gln) polymorphism in the risk of prostate cancer, and the gene-environmental interaction on the development of prostate cancer." (PMID 26101477, 2015). "Our study found that XRCC1 194 (Arg>Trp) polymorphism has interaction with tobacco smoking, alcohol drinking and family history of cancer, which indicated that a significantly gene-environment interaction was shown in the risk of prostate cancer." (PMID 26101477, 2015). "Overall, the results of this meta-analysis show that the XRCC1-Arg399Gln polymorphism may be associated with an increased risk for prostate cancer under the homozygote model and the recessive model." (PMID 25927275, 2015). "The aim of study was to evaluate the influence of TGFB1 C-509T and Leu10Pro, XRCC1 Arg280His and XRCC3 Thr241Met polymorphisms as well as the level of radiation-induced CD8 T-lymphocyte apoptosis (RILA) on adverse effects of RT for prostate cancer (PCa)." (PMID 36494413, 2022). "Except for one protective variant (MTHFR rs1801133) for prostate cancer (OR = 0.684, 95% c.i.=0.565–0.828), six of the seven variant (in MGMT, XRCC1, OGG1, ERCC2 and CASC8) showed risks for prostate cancer." (PMID 26967244, 2016). "Thirteen articles were excluded because the studies had no usable data or were not relevant to the role of the XRCC1-Arg399Gln and Arg280His polymorphisms in prostate cancer risk." (PMID 25927275, 2015).
colon cancer (11 papers, 2008 to 2024). "MMR-deficient colon cancer cells (HCT116) transiently overexpressing MPG or XRCC1 were treated with 5-FU or TMZ and evaluated for viability and metabolic intermediate levels." (PMID 28903334, 2017). "In our study, we observed that only the XRCC1 Gln allelic variants were significantly associated with reduced OS in stage II/III colon cancer patients." (PMID 23894404, 2013). "A significantly shorter OS was observed among stage II/III colon cancer patients with the XRCC1 Gln allelic variants (HR = 1.69, 95% CI = 1.06–2.71), compared to those with XRCC1 Arg/Arg genotype." (PMID 23894404, 2013). "We found a significant relationship between the XPD Lys751Gln allelic variant and OS for CRC patients, particularly for rectal cancer patients, whereas XRCC1 Arg399Gln Gln allele correlated with reduced OS in stage II/III colon cancer patients." (PMID 23894404, 2013). "The poorest OS was observed among the stage II/III colon cancer patients with the XRCC1 Gln allelic variants (HR = 1.69, 95% CI = 1.06–2.71, P = 0.028, FDR = 0.252)." (PMID 23894404, 2013). "To determine whether the T304I mutation disrupts the Polβ/XRCC1 interaction in vivo and in vitro, we used lentiviral transduction to modify the colon cancer cell line HCT116, creating stable cell lines that express either Flag-Polβ(WT) or Flag-Polβ(T304I)." (PMID 31287140, 2019). "In addition, the poorest OS was present among the stage II/III colon cancer patients with both XRCC1 Gln and XPD Gln allelic variants and among the stage II/III rectal cancer patients with both the XRCC1 Arg/Arg and XPD Gln allelic variants." (PMID 23894404, 2013). "The present study showed an inverse correlation between miR-92a-3p and ERCC2 and XRCC1 mRNA expression in SW620 colon cancer cells, which itself proposes a gap in knowledge about the mechanisms of acquired chemoresistance to long-term FOLFOX chemotherapy." (PMID 38659583, 2024). "Particularly, AURKA, which is associated to colon cancer and was recently found to be over expressed also in hematological malignancies, as well as the drug resistant associated genes ABCB1, XRCC1 and CBR3 turned out to be affected." (PMID 35836575, 2022). "The MPG overexpressing colon cancer cells were more sensitive to both 5-FU doses after 24h and 48h in comparison to XRCC1-overexpressed cells (p<0.001)." (PMID 28903334, 2017). "The XRCC1 Arg/Arg genotype was more prevalent in colon cancer patients (56.2%) than in rectal cancer patients (43.3%)." (PMID 23894404, 2013). "In the combined analysis of the XRCC1 and XPD allelic variants, the Kaplan-Meier survival curves showed differences in OS among the 4 allelic variants analyzed in stage II/III colon cancer patients (log-rank test P = 0.087)." (PMID 23894404, 2013). "Through a different mechanism, long-term chemotherapy may induce chemoresistance by upregulation of miR-92a-3p, and subsequent downregulation of ERCC2 and XRCC1 expression in colon cancer, promoting hypermutability and tumor heterogeneity." (PMID 38659583, 2024). "Per this background and based only on the observed changes of ERCC2 and XRCC1 mRNA expression, we may hypothesize that miR-92a-3p improves platinum sensitivity in colon cancer cell lines by downregulation of ERCC2 and XRCC1 expression." (PMID 38659583, 2024). "Imbalancing BER by overexpression of MPG, but not XRCC1, sensitises MMR-deficient colon cancer cells to 5-FU and TMZ and leads to ATP depletion and lactate accumulation." (PMID 28903334, 2017). "We also found that disabling the base excision (BER) repair pathway by depleting XRCC1 or APE1 sensitized colon cancer cells to FdUrd but not 5-FU." (PMID 22194930, 2011). "Given that XRCC1 and APE1 depletion sensitized colon cancer cells to FdUrd, and that PARP plays a key role in BER, we reasoned that PARP inhibitors may sensitize colon cancer cells to FdUrd." (PMID 22194930, 2011).
colon cancer (continued). "Interestingly, we find that MPG, but not XRCC1, overexpression resulted in greater sensitivity to TMZ in colon cancer cells." (PMID 28903334, 2017).
nasopharyngeal carcinoma (10 papers, 2006 to 2023). A carcinoma arising from the nasopharyngeal epithelium. "A study on nasopharyngeal cancer (NPC) found that patients with XRCC1 codon 399 Arg/Arg have a higher risk of developing acute radiation dermatitis." (PMID 34766149, 2021). "Several studies have assessed the association between XRCC1 polymorphisms and cancer risk and prognosis; they have shown that individual susceptibility to cancer is different because of XRCC1 gene polymorphisms in lung, breast, stomach, esophageal and nasopharyngeal cancers." (PMID 36573562, 2023). "It was observed in patients with nasopharyngeal cancers that those with the XRCC1 399Arg/Gln genotype were more likely to experience severe acute radiation mucositis." (PMID 28678827, 2017). "The present study was designed to evaluate the utility of the XRCC1 Arg399Gln and ERCC1 Cys8092Ala SNPs, measured in pretreatment biopsy samples, as predictors of response to radiotherapy in patients with non-metastatic nasopharyngeal carcinoma (NPC)." (PMID 25025378, 2014).